RNF10 (ring finger protein 10)
Description:
E3 ubiquitin-protein ligase that catalyzes monoubiquitination of 40S ribosomal proteins RPS2/us5 and RPS3/us3 in response to ribosome stalling. Part of a ribosome quality control that takes place when ribosomes have stalled during translation initiation (iRQC) or elongation. The ribosome quality control is activated in response to ribosome subunit imbalance, amino acid starvation or downstream the EIF2AK4/GCN2-mediated integrated stress response (ISR). RNF10 acts by mediating monoubiquitination of RPS2/us5 and RPS3/us3: monoubiquitinated RPS2/us5 and RPS3/us3 are then recognized by RIOK3 kinase, leading to 18S non-functional rRNA decay and degradation of the 40S ribosomal subunit. The action of RNF10 in iRQC is counteracted by USP10.
Synonyms: KIAA0262; RIE2
Tractability: PROTAC: ubiquitination databases record sites on it.
Target class: Enzyme; Transferase
Gene: Protein-coding gene on chromosome 12 (120,533,480 to 120,577,588, forward strand). Ensembl gene ENSG00000022840.
Subcellular location: Cytoplasm; Nucleus
Subcellular location (Human Protein Atlas): Nucleoplasm; Mitochondria
Gene Ontology:
Molecular function: protein binding; ubiquitin protein ligase activity; transcription cis-regulatory region binding; metal ion binding
Biological process: nonfunctional rRNA decay; positive regulation of DNA-templated transcription; protein autoubiquitination; protein monoubiquitination; ribosome disassembly; ribosome-associated ubiquitin-dependent protein catabolic process; negative regulation of Schwann cell proliferation; positive regulation of myelination; positive regulation of transcription by RNA polymerase II; postsynapse to nucleus signaling pathway; protein ubiquitination
Cellular component: cytoplasm; cytosolic ribosome; cytosol; nucleus; extrinsic component of postsynaptic density membrane; glutamatergic synapse
Genetic constraint (gnomAD): Loss-of-function variants: 34 observed, 87.28 expected, observed/expected ratio (o/e) 0.39, 90% interval 0.29 to 0.52. The upper end of that interval is the gene's LOEUF score, 0.52, which puts it in group 2 of 6, group 1 being the genes least tolerant of losing a copy. Missense variants: 924 observed, 1,033.4 expected, observed/expected ratio (o/e) 0.89, 90% interval 0.85 to 0.94. Synonymous variants: 358 observed, 371.71 expected, observed/expected ratio (o/e) 0.96, 90% interval 0.88 to 1.05.
Homologues: Orthologues: chimpanzee RNF10 (99% identical), macaque RNF10 (99% identical), dog RNF10 (94% identical), rat Rnf10 (92% identical), guinea pig RNF10 (92% identical), mouse Rnf10 (92% identical), pig RNF10 (79% identical), tropical clawed frog rnf10 (60% identical), rabbit RNF10 (60% identical), zebrafish rnf10 (56% identical), Drosophila melanogaster CG12099 (30% identical).
Diseases named in the same sentence as RNF10 in open-access papers:
RNF10 is named in the same sentence as 12 diseases in open-access papers, as found by Europe PMC text mining. Sharing a sentence is not in itself a finding about the gene and the disease. The quoted sentences say what the papers report.
type 2 diabetes (2 papers, 2020 to 2023). "In Pima Indians, however, a population characterized with high-risk for diet-induced obesity and its sequelae, a strong metabolic association, was found of single-nucleotide polymorphisms in RNF10 with adiposity and type 2 diabetes mellitus (T2DM)." (PMID 37326672, 2023). "It has also been reported to play a role in vascular restenosis and a SNP in RNF10 has been associated with adiposity and type 2 diabetes." (PMID 32245826, 2020).
colorectal adenocarcinoma (1 paper, 2025). The most common type of colorectal carcinoma. "Similarly, NFX1 shows recurrent missense alterations in cutaneous melanoma (SKCM), while RNF10 is frequently mutated in colorectal adenocarcinoma (COAD), highlighting distinct mutation hotspots that may alter protein function in a context-dependent manner." (PMID 40591126, 2025).
intellectual disability syndromes (1 paper, 2016). "Intriguingly, all these genes are mutated or dysregulated in intellectual disability syndromes in humans and/or in the corresponding mouse models, which are characterized by various alterations in dendritic spines, thus suggesting a key role in synaptic effects observed following RNF10 silencing." (PMID 26977767, 2016).
viral infection (1 paper, 2016). "Furthermore, we confirmed by WB analysis the effect of viral infection with pLKO-shRNF10 on protein levels of some of the RNF10 target genes, such as Ophn1, ArhGap4 and ArhGef6." (PMID 26977767, 2016).
cancer (2 papers, 2016 to 2025). A tumor composed of atypical neoplastic, often pleomorphic cells that invade other tissues. "Particularly, the genes that showed the highest mutation frequency across all cancers overall were TAF1, NFX1, and RNF10." (PMID 40591126, 2025). "A very recent study performed in P19 carcinoma cell line and in mouse cerebellar granule cells suggests that RNF10 acts as a positive regulator of neuronal differentiation, as its knockdown reduced the number of cells expressing early and late neuronal markers." (PMID 26977767, 2016).
infection (2 papers, 2017 to 2021). The state of being infected such as from the introduction of a foreign agent such as serum, vaccine, antigenic substance or organism. "We performed an infection with Gram‐positive bacteria L. monocytogenes at a multiplicity of infection of 10 in macrophages and found that the silencing of RNF10 showed a higher production of IL‐6 and TNF‐α after infection for 6 h." (PMID 33249776, 2021). "These functional studies also identified four factors (TRIM32, TRAF3-IP2, RNF10, and KHLH34) that specifically modulate infection with the H1N1pdm09 virus from the 2009 pandemic." (PMID 29202037, 2017).
cardiovascular diseases (1 paper, 2023). "RNF10 may be the next drug target for the treatment of CRC and other related cardiovascular diseases." (PMID 36713029, 2023).
RNF10 also shares sentences with these, for which no sentence is quoted: cervix carcinoma (1 paper); cutaneous melanoma (1); immune dysfunction (1); Sepsis (1); tumor (1).